ENSG00000252640
Synonyms: LOC124903809
Gene: Small nucleolar RNA gene on chromosome 16 (68,630,851 to 68,630,968, reverse strand). Ensembl gene ENSG00000252640.
Gene Ontology:
Biological process: RNA processing
Cellular component: nucleolus
Homologues: Paralogues in human: SCARNA18 (70% identical), SCARNA18B (70% identical).